NF1 (neurofibromin 1)
Diseases named in the same sentence as NF1 in open-access papers (continued):
Sharing a sentence is not in itself a finding about the gene and the disease.
sarcoma (73 papers, 2006 to 2026). A usually aggressive malignant neoplasm of the soft tissue or bone. "In conclusion, this retrospective, multi‐institutional study identified clinical and biological factors associated with the efficacy of ICIs in sarcomas, including novel histological subtypes and specific molecular alterations, such as NF1." (PMID 40911493, 2025). "Studies from 1990 to 201336,37,38,39 found an association between NF1 and rarer sarcomas in our study, but these studies are limited to case reports." (PMID 33734413, 2021). "The neurofibromatosis type 1 (NF1) disease leads to malignancy when the rat sarcoma (RAS) suppressor gene NF1 that encodes neurofibromin is homozygote mutated." (PMID 34449596, 2021). "Some reports also revealed that patients with NF1 had a risk of malignant tumors of the peripheral nerves and other sarcomas or carcinomas." (PMID 34581917, 2021). "A heterogeneous population of sarcomas enrolled on phase 1, including 3 patients with NF1-associated MPNSTs." (PMID 32089640, 2020). "Patients suffering from NF1 inherit germline-inactivating mutations of the NF1 gene that cause deep deregulation of both rat sarcoma (Ras)/mitogen-activated protein kinases (MAPK) and PI3K/mTOR signal transduction networks." (PMID 30657883, 2019). "NF1, a tumour suppressor that functions as a negative regulator of the Ras pathway, is among the most frequently mutated genes in several subtypes of sarcomas." (PMID 28061772, 2017). "MPNST is a rare but highly malignant sarcoma of soft tissues that occurs either sporadically or in association with NF1." (PMID 26993773, 2016). "According to previous reports and the genetic analysis of our case, we believe that the sarcoma component may be formed by the transformation of epithelial components and associated with NF1, MLL2 mutations." (PMID 38903727, 2024). "Indeed, our study heralds a paradigm shift in the early detection of MPNST, a deadly form of sarcoma that escapes modern clinical and imaging surveillance in patients with the NF1 hereditary cancer predisposition syndrome." (PMID 38293154, 2024). "Lastly, NF1 mutations can also be present in sarcomas along with other mutations." (PMID 34659131, 2021). "Moreover, NF1 patients may be at an elevated risk of secondary radiation-induced malignancies, including sarcomas." (PMID 41487701, 2026). "Although rare in tumors such as gastric cancer, sarcoma, and renal cell carcinoma, recent finding that NF1 mutations are enriched (11%) in oncogene-negative subset of lung adenocarcinomas, and our finding suggests novel therapeutic opportunities for the subset of patients with NF1 mutations." (PMID 26859683, 2016).
sarcoma (continued). "Although BRCA mutations are rare in sarcomas, alterations in ATM and NF1 have been reported in myxofibrosarcoma, suggesting a potential therapeutic vulnerability." (PMID 41200607, 2025). "The NF1 gene product, neurofibromin, is a negative regulator of rat sarcoma (Ras)/mitogen-activated protein kinases (MAPK) and PI3K/mTOR signals." (PMID 36830839, 2023). "Neurofibromin, the gene product of the NF1 gene, participates in controlling the pathway of rat sarcoma (RAS) homologue in man." (PMID 38111842, 2023). "Nevertheless, we believe this model represents a valuable resource for the NF1 and sarcoma community for future mechanistic and therapeutic investigations of MPNSTs in immunocompetent hosts." (PMID 35852856, 2022). "The positive rate of NF1 protein in the UPS sarcoma tissue was decreased compared to that in the adjacent tissue, and the difference was statistically significant (p < 0.05)." (PMID 35559021, 2022). "In this study, we detected the mRNA and protein expression of NF1 in the UPS sarcoma tissue and adjacent normal tissue and analyzed the clinicopathological characteristics." (PMID 35559021, 2022). "Removal of glutamine from the media significantly (p<0.0005) decreased cell viability only in the NF1 mutant/null cell lines, MPNST, ST8814 and S462 compared to wild-type NF1 sarcoma cell lines, LS141, CHP100 and STS26T." (PMID 29212209, 2017). "Perhaps this is not surprising, given that most of the tumors from the irradiated Nf1+/- mice are sarcomas derived from muscle tissue, where Grb10 has a more prominent role than Grb14." (PMID 26000738, 2015). "In 1 case (a patient with NF1), the second tumor was a sarcoma that had developed outside the central nervous system." (PMID 26098902, 2015). "This suggested that together with losses at Cdkn2a and Nf1 loci the recurrent duplications of these chromosomes belong to early events in sarcoma development." (PMID 21533183, 2011). "Across the cohort, no cases of radiation-induced secondary malignancies or sarcomas were observed, which is particularly reassuring given the long follow-up and theoretical susceptibility of NF1 patients to radiation-induced tumors." (PMID 41487701, 2026). "Moreover, the methylome profile of the three cell lines obtained from tumors SP‐01, NF1‐08, and NF1‐09 was compared with other sarcomas." (PMID 37798904, 2024). "Next, we studied the effects of ATRX loss in NF1-deficient MPNST and sarcoma cell lines." (PMID 35740680, 2022).
sarcoma (continued). "In contrast, ATRX knockdown in the ALT-negative, NF1-associated sarcoma line JHH-CRC65 did not increase sensitivity to either ATR inhibition or temozolomide treatment." (PMID 35740680, 2022). "Pathological assessment of PTEN−/−;NF1−/− tumors revealed regions of hypercellularity with occasional mitoses, and in one out of four tumors, there were biphasic dense glial and loose mesenchymal/sarcoma morphologies, typical of gliosarcoma." (PMID 31992716, 2020). "The remaining patients in this group (3/98; 3%) were sarcoma (GIST) patients with NF1 mutations indicating they should not receive imatinib, or NSCLC patients with EGFR T790M mutations (3/98; 3%) indicating resistance to first and second generation EGFR TKIs." (PMID 31384390, 2019). "In addition to shared clonal abnormalities, additional aberrancies were detected in the sarcoma tumor cells, including deletion of a subclone of BRAF (G466A), loss of TRAF3 R505 and new clonal mutations in NF1 and TNFAIP3." (PMID 29463311, 2018). "To determine whether this effect in tumors was Nf1 dependent, we expressed Grb10 in the sarcoma line 963, which arose in a wildtype mouse and expresses neurofibromin protein." (PMID 26000738, 2015). "In conclusion, MPNSTs arising in patients with NF-1 are high grade sarcomas with dismal prognosis." (PMID 25317349, 2014). "In conclusion, MPNSTs arising in patients with NF1 are high grade sarcomas with short survival." (PMID 25317349, 2014). "MPNST are invasive sarcomas with extremely poor prognosis, and their development may correlate with internal tumor load of patients with NF1." (PMID 23618374, 2013). "Thus, the disruption of Nf1 in sarcomas from MD-mice parallels specific - non myogenic - subtypes of human soft-tissue sarcomas and suggests a more general role for Nf1-lesions in the genesis of mesenchymal cancers." (PMID 21533183, 2011). "This study offers one of the largest multicentric analyses of advanced sarcoma patients treated with immune checkpoint inhibitors (ICIs), highlighting the predictive value of histological subtype and identifying potential roles for specific molecular alterations, such as NF1." (PMID 40911493, 2025). "These clinical reports are in line with the observation that in MD mice, sarcomas share nonrandom genomic alterations including frequent loss of TS (such as Cdkn2a or Nf1), amplifications of oncogenes (Met, Jun), recurrent duplications of whole chromosomes 8 and 15, and DNA damage." (PMID 35790299, 2022). "FISH for NF1 and p16 deletions, which are observed frequently in high-grade MPNSTs, might be a useful ancillary diagnostic tool for differentiating MPNST from other mimicking spindle cell and pleomorphic sarcomas." (PMID 34461930, 2021). "FISH for NF1 and p16 deletions, frequently observed in high-grade MPNSTs, might be a useful ancillary diagnostic tool for differentiating MPNST from other mimicking spindle cell and pleomorphic sarcomas." (PMID 34461930, 2021). "Furthermore, Chr8 gain has been described in Ewing sarcoma and other pediatric soft-tissue sarcomas and, therefore, may be a critical event for numerous sarcomas, in addition to NF1-MPNST." (PMID 33591953, 2021).
sarcoma (continued). "Herein, we show that ATRX is aberrantly expressed in the majority of MPNSTs and that this aberrant expression is associated with poor overall survival in NF1-associated MPNSTs, which suggests that ATRX expression could be evaluated as a prognostic biomarker for these aggressive sarcomas." (PMID 29796169, 2018). "A third tumor, NF1‐09, was classified as an MPNST although it has PRC2 active, which might account for the NF1‐09‐derived cell line clustering in the MPNST‐like sarcoma group when using a methylome classifier." (PMID 37798904, 2024). "Lesions of the Nf1 gene (exons 23 and/or 56) were more frequently found in Dmd −/− (34%) and Dmd −/− Dysf −/− sarcomas (31%) as opposed to Dysf −/− (14%) or Dmd −/− Capn3 −/− (18%)." (PMID 21533183, 2011). "In our larger study, we report a preponderance of brain/CNS and connective tissue tumours, whereas although sarcomas were reported in 7% of individuals with NF1, this Swedish study reported no individuals with CNS malignancy." (PMID 16786042, 2006). "In the 68 cases of the adjacent normal tissue, there were 48 cases with NF1 high protein expression and 20 cases with NF1 low/ no protein expression; In the 68 cases of the UPS sarcoma tissue, there were 27 cases with NF1 high protein expression and 41 cases with NF1 low/no protein expression." (PMID 35559021, 2022). "They demonstrated the specific deletion of NF1 and p16 in MPNST and indicated that homozygous and heterozygous deletion of p16 might distinguish MPNST from benign nerve sheath tumor and other histologically mimicking sarcomas." (PMID 34461930, 2021). "Patient data from the prospectively collected UCLA sarcoma database (1974–2011, n = 113 MPNST patients) and 39 published studies on MPNST patients (n = 916) were analyzed for age of onset differences between sexes and between NF-1 and spontaneous MPNST patients." (PMID 25398666, 2014).
lung carcinoma (71 papers, 2009 to 2025). "Somatic NF1 pathogenic variants are found in a variety of malignancies, including desmoplastic melanoma, lung cancer, and ovarian carcinoma, yet these sporadic cancers are not commonly associated with the NF1 tumor predisposition syndrome." (PMID 38473354, 2024). "The present study clearly demonstrated a relationship between NF1 mutations and various oncogenes and suppressor genes of lung cancer." (PMID 35702826, 2023). "In the present study, we retrospectively analyzed the clinicopathological characteristics, molecular profiles, and prognostic features of NF1 mutations in EGFR mutant lung cancer patients." (PMID 35702826, 2023). "Our data showed that the clinicopathological features of lung cancer patients with NF1 mutations were clearly enriched in older (p < 0.001), male (p < 0.001), and smoking (p < 0.001) patients." (PMID 35702826, 2023). "The clinical and pathological characteristics of Chinese lung cancer patients with NF1 mutations and wild‐type NF1 were compared." (PMID 35702826, 2023). "The Cancer Genome Atlas (TCGA) Research Network reported that NF1 gene mutations are related to the development of lung cancer." (PMID 35702826, 2023). "In lung cancer, NF1 gene mutations occur in approximately 7.0%–11.8% cases of LUAD7, 8, 9, 13, 17, 18 and 10.3%–12.0% cases of LUSC in Western population." (PMID 35702826, 2023). "NF1 mutations have been identified both in NF1 patients and in individuals with sporadic brain, breast, or lung cancer." (PMID 35625983, 2022). "Similar NF1/GOSR1 gene rearrangements causing inactivation of the NF1 gene have also been reported in lung cancer, where they are thought to play a role in the onset of adenocarcinomas lacking known driver mutations." (PMID 34944796, 2021). "KRAS mutation in endometrial cancer and NF1 mutation in lung cancer case were annotated resistance information only in the OKR system." (PMID 31383922, 2019). "Lung cancers with NF1 mutations have also been characterized by downstream activation of Ras signaling." (PMID 31867044, 2019). "Consistent with our findings, mutation and subsequent loss of the tumour suppressor function of NF1 has been reported in lung cancer cells which have acquired resistance to the SRC inhibitor dasatinib, and this was associated with active RAS-MAPK signalling." (PMID 29435137, 2018). "The challenges of elucidating the mechanisms of NF1 deficiency are demonstrated in the recent study on reduced NF1 expression as a driver of resistance to EGFR inhibitor in lung cancer." (PMID 25026295, 2014). "We analyzed NF1 mutations in a large‐scale cohort of Chinese lung cancer patients." (PMID 35702826, 2023). "This study was more clearly showed the effect of NF1 mutations on EGFR mutant lung cancer patients." (PMID 35702826, 2023). "NF1 mutations were more common in older, male, and smoking lung cancer patients, and could define a specific population with a distinct clinical profile." (PMID 35702826, 2023). "Somatic NF1 mutations were present in 4.2% (135/3220) of Chinese lung cancer patients." (PMID 35702826, 2023). "In this sense, we have discovered that mutations in the NF1 tumor suppressor gene could be exerting an as yet unknown function in lung cancer." (PMID 35884384, 2022).